INPP4B (inositol polyphosphate-4-phosphatase type II B)
Diseases named in the same sentence as INPP4B in open-access papers (continued):
Sharing a sentence is not in itself a finding about the gene and the disease.
melanoma (continued). "Several studies have demonstrated that SGK3 contributes to INPP4B-mediated cell proliferation in colon cancer and a subset of melanomas cells." (PMID 29343273, 2018). "The impact of INPP4B expression has been previously reported in four of these cancers: bladder cancer, lung cancer, melanoma, and AML." (PMID 29415082, 2018). "LOH of the gene region of INPP4B(4q31.21) occurs in basal-like breast tumours (55.6%), ovarian cancers (39.8%) and melanomas (21.6%)." (PMID 28082369, 2017). "In support, examination of representative fresh melanoma isolates with various levels of INPP4B showed that melanomas with high, intermediate, and low expression of INPP4B displayed progressively decreasing levels of phosphorylated (activated) SGK3." (PMID 26573229, 2015). "Although shRNA knockdown of INPP4B did not impinge on phosphorylation of SGK1, it inhibited SGK3 activation in Mel-RM and ME4405 cells, suggesting that INPP4B preferentially affects SGK3 activation in melanoma cells." (PMID 26573229, 2015). "Collectively, these results indicate that INPP4B activates PI3K/SGK3 signalling to drive melanoma cell proliferation independently of Akt." (PMID 26573229, 2015). "On the other hand, introduction of exogenous INPP4B resulted in increased melanoma cell and melanocyte proliferation and anchorage-independent growth of melanocytes." (PMID 26573229, 2015). "The role of inhibition of SGK3 in suppression of melanoma xenograft growth was confirmed by transplanting INPP4B stable knockdown Mel-RM cells co-introduced with myr-SGK3 into nu/nu mice." (PMID 26573229, 2015). "In this report, we present evidence that the 4-phosphatase INPP4B has an unexpected oncogenic role in human melanoma." (PMID 26573229, 2015). "The differences in the expression of miR-494 and/or miR-599 between melanoma cell lines with different levels of the INPP4B protein were confirmed by qPCR." (PMID 26573229, 2015). "We focused on examination of the functional significance of INPP4B upregulation in melanoma cells by knockdown of INPP4B with two individual shRNAs using lentiviral transduction in Mel-RM and ME4405 cells." (PMID 26573229, 2015). "To understand the mechanism responsible for INPP4B upregulation in melanoma cells, we quantitated the expression of INPP4B mRNA in the panel of melanoma cell lines in which the expression of INPP4B at the protein level has been characterized." (PMID 26573229, 2015). "When the binding regions for miR-494 and miR-599 were mutated simultaneously, there was a further increase in the promoter activity, suggesting that miR-494 and miR-599 function corporately to target the 3′UTR of INPP4B in melanoma cells." (PMID 26573229, 2015). "Our results also revealed that loss of miR-494 and miR-599 due to gene copy number reduction was responsible for upregulation of INPP4B in melanoma cells." (PMID 26573229, 2015). "Collectively, these results suggest that, despite its tumour suppressive role mediated by inhibition of activation of Akt in MCF-7 cells, INPP4B promotes melanoma cell proliferation independently of activation of Akt." (PMID 26573229, 2015). "In this report, we provide evidence that INPP4B is upregulated in a subset of melanomas and plays a role in melanoma cell proliferation independently of Akt through activating PI3K/SGK3 signalling." (PMID 26573229, 2015). "While INPP4B was expressed at undetectable or low levels in most of the melanoma cell lines (6/10), it was elevated in the others with varying levels (4/10)." (PMID 26573229, 2015). "We also examined representative fresh melanoma isolates sampled by their INPP4B protein levels for the expression of miR-494 and miR-599." (PMID 26573229, 2015). "As anticipated and in contrast to its effect on melanoma cells, INPP4B knockdown enhanced Akt activation and promoted proliferation in MCF-7 cells that were used as a control." (PMID 26573229, 2015).
melanoma (continued). "We performed a comprehensive analysis of INPP4B overall gene expression in metastatic melanomas compared to primary melanomas using the Oncomine database." (PMID 25868852, 2015). "Although INPP4B was commonly detected with weak to moderate staining in nevi, its expression was noticeably elevated in a subset of melanomas." (PMID 26573229, 2015). "While INPP4B was upregulated in a subset of melanomas, knockdown of INPP4B caused reduction in SGK3 activation, which led to inhibition of proliferation of melanoma cells in vitro and retardation in melanoma growth in a xenograft model." (PMID 26573229, 2015). "PCR analysis confirmed that the fragment of DNA cloned into the luciferase reporter plasmids was indeed present at the endogenous 3′UTR of INPP4B in melanoma cells." (PMID 26573229, 2015). "The increased expression of INPP4B in a subset of melanomas was confirmed in 20 fresh metastatic melanoma isolates using Western blot analysis." (PMID 26573229, 2015). "An important finding of this study is the identification of loss of miR-494 and miR-599 as the mechanism responsible for upregulation of INPP4B in melanoma cells." (PMID 26573229, 2015). "While INPP4B knockdown inhibited melanoma cell proliferation and retarded melanoma xenograft growth, overexpression of INPP4B enhanced melanoma cell and melanocyte proliferation and triggered anchorage-independent growth of melanocytes." (PMID 26573229, 2015). "We analyzed LRRK2, ADCY3, and INPP4B DNA methylation and expression profiles in human melanoma cohorts to determine whether the murine model data are applicable to human melanoma biology." (PMID 35075772, 2022). "INPP4B may have a dual oncogenic/tumor suppressor role and was found as an oncogenic regulator in colon cancer, acute myeloid leukemia and in a subset of melanomas." (PMID 35158790, 2022). "However, some recent studies have reported that INPP4B is highly expressed in colon cancer, acute myeloid leukaemia and melanoma, where it serves as an oncogene and is a positively correlated with poor clinical outcomes." (PMID 33879096, 2021). "In addition, many subsequent reports have shown that INPP4B protein expression is reduced in melanoma, ovarian, and prostate cancers." (PMID 34035258, 2021). "In melanoma, one study reported that low levels of INPP4B expression was associated with tumor progression, while another study reported a SGK3-dependent oncogenic role for INPP4B in a high expressing subset of the same disease." (PMID 29415082, 2018). "INPP4B knockdown promotes AKT-mediated melanoma cell growth and proliferation." (PMID 28082369, 2017). "INPP4B shRNA knockdown attenuated melanoma cell proliferation and xenograft tumour growth, whereas INPP4B overexpression enhanced cell proliferation and promoted melanocyte anchorage-independent cell growth, driven by INPP4B-mediated activation of SGK3 in an AKT-independent manner." (PMID 28082369, 2017). "Similarly, INPP4B protein expression is progressively lost in more advanced stages of human melanocytic tumours, and its shRNA-mediated knockdown in melanoma cell lines enhanced AKTSer473 phosphorylation, proliferation, migration and in vivo tumour growth." (PMID 28082369, 2017). "None of the melanoma cell lines harboured nonsynonymous mutations in the INPP4B gene as determined by sequencing all the 27 exons (including the intron/exon boundaries) of the gene." (PMID 26573229, 2015). "Since SGKs are highly homologous to and share substrate specificity with Akt, we tested whether they are involved in INPP4B-mediated promotion of melanoma cell proliferation." (PMID 26573229, 2015). "Given that melanoma cells are highly heterogeneous, it is conceivable that the relative importance of the two miRs in suppression of INPP4B may also be highly variable depending on cells and context in question." (PMID 26573229, 2015).
melanoma (continued). "The lipid phosphatase inositol polyphosphate 4-phosphatase type II (INPP4B) has been described as a tumor suppressor in the PI3K/Akt pathway with loss of expression found most pronounced in breast, ovarian cancer and melanoma." (PMID 25868852, 2015). "We found significantly lower INPP4B expression in metastatic melanomas compared to primary lesions corroborating earlier findings that loss of INPP4B expression may modulate the metastatic potential of tumors." (PMID 25868852, 2015). "Indeed, SGK3 activation (phosphorylation) was elevated in melanoma cell lines expressing relatively high levels of INPP4B compared with those with low levels." (PMID 26573229, 2015). "To examine whether the elevated expression of INPP4B affects melanoma growth in vivo, we transplanted Mel-RM cells with or without INPP4B stably knocked down into nu/nu mice." (PMID 26573229, 2015). "Indeed, we found that miR-494 and miR-599 cooperatively suppressed INPP4B in melanoma cells, which were nevertheless lost either individually or concurrently in a proportion of melanomas." (PMID 26573229, 2015). "Gene expression data of primary melanomas from both TCGA and Bogunovic Cohorts showed that higher INPP4B gene expression values correlated with poor patient survival, underscoring the prognostic importance of INPP4B DNA methylation and gene expression in melanoma patients." (PMID 35075772, 2022). "Indeed, we have found that INPP4B functions as an oncogenic driver in human melanoma." (PMID 26573229, 2015). "Similarly, whether INPP4B is targetable in the treatment of melanoma needs further investigation, but given that INPP4B functions as a tumour suppressor in many other tissues, direct inhibition of INPP4B in vivo needs to be evaluated with a great caution." (PMID 26573229, 2015). "Alternatively, suppression of INPP4B indirectly through restoring miR-494 and miR-599 may be a useful strategy, which may lead to selective inhibition of INPP4B in melanoma cells, as regulation of target expression by miRs is known to be highly cell type-dependent." (PMID 26573229, 2015). "Indeed, overexpression of miR-494 or miR-599 downregulated INPP4B, reduced SGK3 activation, and inhibited melanoma cell proliferation, whereas introduction of anti-miR-494 or anti-miR-599 upregulated INPP4B, enhanced SGK3 activation, and promoted melanoma cell proliferation." (PMID 26573229, 2015). "In this context, INPP4B has already been described as an oncogenic driver through phosphorylation and activation of SGK3 in a subset of melanoma and colon carcinoma." (PMID 36993823, 2023). "miR-605 also targets INPP4B, a phosphatase that functions as an oncogenic driver through activating SGK3 kinase in melanoma tissue." (PMID 35645336, 2022). "More recently, some unexpected findings have indicated that INPP4B is significantly upregulated, and plays an oncogenic role in AML, melanoma and colon cancer by activating SGK3, and that it is associated with patient prognosis." (PMID 33879096, 2021). "Here we report that INPP4B can function as an oncogenic driver through activation of serum- and glucocorticoid-regulated kinase 3 (SGK3) in melanoma." (PMID 26573229, 2015). "Our results extended this observation by showing that SGK3 similarly played a role in proliferation of wild-type BRAF melanoma cells (Mel-RM and ME4405) and melanocytes, at least when the upstream signal was driven by INPP4B." (PMID 26573229, 2015). "However, several studies have reported an increased INPP4B expression, e.g., in AML, colon cancer, and a subset of melanomas revealing the paradoxical role of an oncogene." (PMID 36993823, 2023). "However, increased INPP4B expression has been reported for several tumor entities, e.g., AML, melanoma, and colon cancers, suggesting the oncogenic potential of INPP4B (for review see:)." (PMID 36993823, 2023). "Thus, miR-605 functions as a tumor suppressor by inhibiting INPP4B expression and SGK3 activity in melanoma." (PMID 35645336, 2022).
melanoma (continued). "The results showed that melanomas with no or low expression of INPP4B displayed relatively high levels of miR-494 and miR-599, whereas those expressing relatively high levels of INPP4B exhibited reduction in miR-494 and/or miR-599." (PMID 26573229, 2015). "Noticeably, INPP4B-mediated melanoma cell proliferation was not related to activation of Akt, but was mediated by SGK3." (PMID 26573229, 2015). "While the tumour suppressive role of INPP4B in these tissues has been exclusively attributed to its ability to inhibit PI3K/Akt signalling, INPP4B did not appear to impinge on Akt activation in melanoma cells and melanocytes." (PMID 26573229, 2015). "In agreement with observations in melanoma, our functional study revealed no obvious effect of INPP4B expression on the proliferation and survival of NPC cells in vitro." (PMID 25126743, 2014). "Notably, INPP4B was found to serve as a tumor suppressor gene in melanoma via regulating PI3K/Akt signaling, which impacts the proliferative, invasive, and tumorigenic capacity of melanoma cells." (PMID 38474285, 2024). "Collectively, these results identify upregulation of INPP4B as an oncogenic mechanism through activation of SGK3 in a subset of melanomas, with implications for targeting INPP4B and restoring miR-494 and miR-599 as novel approaches in the treatment of melanomas with high INPP4B expression." (PMID 26573229, 2015). "Interestingly, neither 5azaCdR nor TSA substantially increased Inpp4b expression in 4C11‐ cells, indicating that other mechanisms might regulate expression of this gene in nonmetastatic melanoma cells." (PMID 35075772, 2022).
acute myeloid leukemia (18 papers, 2015 to 2023). Acute myeloid leukemia (AML) is a group of neoplasms arising from precursor cells committed to the myeloid cell-line differentiation. "Other studies have already demonstrated that INPP4B is associated with chemoresistance in acute myeloid leukemia (AML;) and induces chemosensitivity of human hepatocellular carcinoma cells lines." (PMID 36993823, 2023). "Moreover, INPP4B is associated with chemoresistance and poor outcome of patients with acute myeloid leukaemia (AML)." (PMID 26573229, 2015). "The present study aimed to investigate the underlying role of interferon-regulatory factor 2 (IRF2)–inositol polyphosphate-4-phosphatase, type-II (INPP4B) axis in the regulation of autophagy in acute myeloid leukemia (AML) cells." (PMID 30876449, 2019). "Our group has demonstrated that INPP4B expression in acute myeloid leukemia regulates lysosomal biogenesis and functions which are crucial for leukemia stem cell maintenance, differentiation, and chemoresistance." (PMID 35760104, 2022). "INPP4B enhances the chemoresistance of some cancers including acute myeloid leukemia and colorectal cancer." (PMID 36612130, 2022). "miR222-3p is highly expressed in BMSC-derived exosomes, which is delivered to negatively regulate the IRF2/INPP4B signaling pathway, thus, inhibiting proliferation and promoting apoptosis in acute myeloid leukemia (AML) cells by targeting IRF2." (PMID 36338118, 2022). "However, INPP4B paradoxically functions as an oncogene in several cancers, including acute myeloid leukemia (AML) and colon cancer where its overexpression promotes chemoresistance and tumor growth." (PMID 36612130, 2022). "Interestingly, overexpression of INPP4B may paradoxically promote tumorigenesis in acute myeloid leukemia independently of the INPP4B phosphatase activity through mechanisms that remain to be explained." (PMID 28031327, 2017). "In recent studies, the overexpression of INPP4B in AML cells enhancescolony-forming potential and induces chemotherapy resistance in acute myelocytic leukemia (AML) patients." (PMID 37064094, 2023). "Consistent with our data, it has been demonstrated that INPP4B overexpression inhibits cervical and human hepatocellular carcinoma (HCC) as well as multiple myeloma and acute myeloid leukemia, cell proliferation, and induces caspase-3-mediated apoptosis in HCC cell lines." (PMID 36993823, 2023). "In acute myeloid leukemia (AML), BM-MSC-derived miR-222-3p within sEVs induced the downregulation of IRF2/INPP4B signaling and increased apoptosis of the AML cell line THP-1." (PMID 37762393, 2023). "Along this line, INPP4B knockdown leads to a reduction in p-SGK3 levels, but did not influence AKT activation in NPM1-mutated OCI-AML3 acute myeloid leukemia cells and INPP4B expression is not correlated with alterations in AKT phosphorylation in leukemia, suggesting an AKT-independent mechanism." (PMID 36993823, 2023). "For example, miR222-3p, which is highly expressed in BMMSC-EVs, suppresses acute myeloid leukemia (AML) cell proliferation and promotes apoptosis by targeting the IRF2/INPP4B signaling pathway." (PMID 37242693, 2023).
ovarian cancer (13 papers, 2011 to 2021). A primary or metastatic malignant neoplasm involving the ovary. "Loss of INPP4B protein expression in breast and ovarian cancer cells is associated with decreased patient survival rates." (PMID 22121480, 2012). "Inositol polyphosphate 4-phosphatase type II (INPP4B), is tumor suppressor in implicated in many cancers such as prostate, breast, and ovarian cancers and also potentially in leukemia." (PMID 23455493, 2012). "Given that INPP4B loss has been found in 40% of ovarian cancer patients, this study provides the rationale for establishing INPP4B as a biomarker of PARP inhibitor response, and consequently offers novel therapeutic options for a significant subset of patients." (PMID 25868852, 2015). "As a novel factor in the PI3K signaling pathway, INPP4B has been found to play a tumor suppressive role in prostate, breast, and ovarian cancers, and possibly in leukemia." (PMID 29343273, 2018). "Stable knockdown cell pools of the human ovarian cancer cell lines Ovca429 and Ovca433 expressing shRNA hairpins directed against Renilla luciferase, INPP4B, PTEN and BRCA1 were generated." (PMID 25868852, 2015). "Recently, another lipid phosphatase, Inositol Polyphosphate 4-phosphatase type II (INPP4B), has emerged as a potential tumor suppressor in prostate, breast, and ovarian cancers and possibly in leukemia." (PMID 21487159, 2011). "However, we demonstrate that INPP4B loss and subsequent activation of the PI3K/Akt pathway resulted in significant sensitization towards PARP inhibition suggesting an independent role for INPP4B in HR in ovarian cancer." (PMID 25868852, 2015). "Similarly, loss of INPP4B in ovarian cancer was associated with shorter OS and higher rates of lymph node metastasis." (PMID 29415082, 2018). "We next determined whether lack of competent HR due to INPP4B loss might sensitize INPP4B-deficient human ovarian cancer cells to PARP inhibition." (PMID 25868852, 2015). "Similar to the phosphatase activity of PTEN in the PI3K/AKT signaling pathway, inositol polyphosphate 4-phosphatase type II (INPP4B) is able to suppress the PI3K/AKT signaling pathway and behaves as a tumor suppressor in at least breast and ovarian cancers." (PMID 22666248, 2012). "Therefore, we characterized INPP4B and PTEN expression levels, as well as PI3K/Akt (phosphoS473 Akt) and MAPK pathway (phospho-p42/44) activation in ten different human ovarian cancer cell lines." (PMID 25868852, 2015).